CD72 (CD72 molecule)
Diseases named in the same sentence as CD72 in open-access papers (continued):
Sharing a sentence is not in itself a finding about the gene and the disease.
chronic graft versus host disease (1 paper, 2025). Chronic graft versus host disease (GVHD) is a complication that can occur after a stem cell or bone marrow transplant in which the newly transplanted donor cells attack the transplant recipient's body. "In another study that investigated lncRNA expression in chronic graft-versus-host disease, three lncRNAs (NONHSAT142151, NONHSAT040475 and FR118417) were found to strongly correlate with the expression of mRNAs related to the BCR signaling pathway (BTK, CD72, DAPP1, LILRB3, NFKBIE, RASGRP3)." (PMID 39940921, 2025).
Chronic Lymphocytic Leukemia (1 paper, 2018). "Isolated antibodies were found to target six different receptors on Chronic Lymphocytic Leukemia cells; CD21, CD23, CD32, CD72, CD200, and HLA-DR of which CD32, CD200, and HLA-DR appeared as the most potent targets for antibody-based cytotoxicity treatment." (PMID 30182064, 2018).
cognitive decline (1 paper, 2025). "FCAMR and CD72, both involved in B-cell activation and antibody responses, were negatively correlated with global cognition in RHI, underscoring chronic immune activation as a driver of RHI-related cognitive decline." (PMID 40524252, 2025).
colorectal cancer (1 paper, 2023). A primary or metastatic malignant neoplasm that affects the colon or rectum. "In addition, CD72 has been identified as a prognostic gene in the tumor microenvironment of colorectal cancer." (PMID 37980541, 2023).
COVID-19 (1 paper, 2021). A disease caused by infection with severe acute respiratory syndrome coronavirus 2. "BCR inhibitory gene expression was limited, but CD22 was detectable across B cell subsets in asymptomatic COVID-19, while FCGR2B, CD72 and PTPN6 expression was evident in B cells in severe COVID-19." (PMID 33879890, 2021).
glomerulonephritis (1 paper, 2018). A renal disorder characterized by damage in the glomeruli. "Both CD72−/−Faslpr/lpr mice and MRL.Faslpr mice produce large amounts of autoantibodies such as anti-DNA antibody and develop glomerulonephritis with severe histological changes at 6 months of age." (PMID 30333834, 2018).
myeloid leukemia (1 paper, 2020). A clonal proliferation of myeloid cells and their precursors in the bone marrow, peripheral blood, and spleen. "Most importantly, this approach identified multiple surface molecules whose role in myeloid leukemia remains unknown; these included integrin β7, siglec-F (CD170), CD72, LPAM-1 (integrin α4β7) and syndecan-1 (Sdc1, CD138)." (PMID 33243988, 2020).
myocardial infarction (1 paper, 2023). Gross necrosis of the myocardium, as a result of interruption of the blood supply to the area, as in coronary thrombosis. "Furthermore, the proteins CD47 and CD72, which are associated with integrin, exert an influence on the intercommunication between macrophages and cardiac myocytes after myocardial infarction (MI)." (PMID 37817547, 2023).
neuroblastoma (1 paper, 2025). Neuroblastoma (NB) is the most common solid, extracranial childhood tumor. "Indeed, strategies to upregulate surface ALK using ALK inhibitors in neuroblastoma or to upregulate surface CD72 using SHIP1 inhibitors in B-ALL significantly improves CAR T-mediated killing." (PMID 40931013, 2025).
non-small cell lung carcinoma (1 paper, 2023). A group of at least three distinct histological types of lung cancer, including non-small cell squamous cell carcinoma, adenocarcinoma, and large cell carcinoma. "SEMA4D binds to CD72 to promote the activity of CD8+ T‐cells in non‐small cell lung cancer patients." (PMID 37701532, 2023).
Obesity (1 paper, 2024). Accumulation of substantial excess body fat. "Thus, the two DEGs between these two groups (Cd72 and EiF3jl) may be due to a recent history of obesity that had yet to resolve upon the normalization of body mass." (PMID 39273278, 2024).
rectal tumor (1 paper, 2024). "In our study, FOXP3(r = 0.179), CD72(r = 0.155), RUNX1(r = 0.327), LAG3(r = 0.194), CTLA4(r = 0.236) have a positive correlation with AP3M2 in Colon Neoplasm, but no irrelevancy in rectal tumor." (PMID 38177168, 2024).
renal carcinoma (1 paper, 2023). A carcinoma arising from the epithelium of the renal parenchyma or the renal pelvis. "The expression of CD72 in renal cancer cells was higher than in normal renal cells." (PMID 37980541, 2023).
sarcoidosis (1 paper, 2016). Sarcoidosis is a multisystemic disorder of unknown cause characterized by the formation of immune granulomas in involved organs. "Cluster of Differentiation 72 (CD72) is a CD5 co-ligand involved in hypersensitivity reactions and sarcoidosis, highly expressed in pulmonary alveolar macrophages." (PMID 27814717, 2016).
Sepsis (1 paper, 2022). Sepsis is defined as life-threatening organ dysfunction caused by a dysregulated host response to infection. "In addition, the low percentage of CD72+/CD19+ B cells after 3–4 days after sepsis correlates with the reduction of plasma immunoglobulin M levels and is an independent predictor of 28-day mortality in patients with sepsis." (PMID 36425582, 2022).
Stroke (1 paper, 2025). Sudden impairment of blood flow to a part of the brain due to occlusion or rupture of an artery to the brain. "CD72 was recently revealed as a pro-inflammatory factor in microglia in a mouse model of stroke: it is upregulated after stroke, and selective knockdown of CD72 in microglia reduced infarct volume, reduced inflammatory cytokine production, and reduced neuronal apoptosis." (PMID 40501958, 2025).
type 1 diabetes mellitus (1 paper, 2021). A chronic condition characterized by minimal or absent production of insulin by the pancreas. "For instance, CD22 and CD72 inhibited the proliferation of regulatory B cells, which can regulate MS and type 1 diabetes mellitus (T1D)." (PMID 34539413, 2021).
cancer (10 papers, 2015 to 2025). A tumor composed of atypical neoplastic, often pleomorphic cells that invade other tissues. "For the lymphoid-derived cancer cell lines next to the specific surface markers (e.g., CD72, LAIR) associated with T/B-cells, we identified FLT3, HOXA9, MYC, and HEXIM1 as top genes driving the difference between the samples." (PMID 31253180, 2019). "Sema4D acts as a ligand for receptor plexins (B1, B2, and C1) and CD72 and has been reported to be involved in platelet and neutrophil activation, angiogenesis, and cancer metastasis." (PMID 30538782, 2018). "In cancer zone B, the SEMA4 pathway relied on Sema4a-Plxnb2, Sema4d-Cd72, and Sema4d-Plxnb2 interactions, with Sema4a/d-Plxnb2 showing particularly strong communication between cancer_macro 1 cells." (PMID 40723284, 2025). "The expression of genes in NPC tissues and normal tissues was observed, and it was found that the expression of BTK, CD72, PTPN6, and VAV1 was different in cancer and normal tissues, and the expression was lower in both cancer and normal tissues." (PMID 35957889, 2022). "With regard to B cells, changes included decreases in the gene expression of CD19, CD22, CD72, IKZF3 and GCSAM in cancer patients compared to healthy donors." (PMID 28936253, 2016).
tumor (10 papers, 2015 to 2025). "According to ssGSEA and Spearman correlation analysis, CD72 expression was significantly associated with tumor immune cells and immune checkpoints." (PMID 37980541, 2023). "Our study suggests that CD72 is associated with tumor immunity and may be a biomarker relevant to the diagnosis and prognosis of KIRC patients." (PMID 37980541, 2023). "CD72 is also closely associated with the tumor microenvironment." (PMID 37980541, 2023). "These pleiotropic effects make Dihydroergotamine a biologically plausible candidate for repurposing in oncology, especially if it can modulate CD72 activity in immune cells within the tumor milieu." (PMID 41148223, 2025). "All these results suggest that up-regulation of CD72 expression can suppress the anti-tumor immune response in KIRC patients." (PMID 37980541, 2023). "Therefore, CD72 is expected to be a potential diagnostic and prognostic biomarker for KIRC and a new target for anti-tumor drug development." (PMID 37980541, 2023). "In this study, CD72 expression was significantly correlated with the Pathologic T stage, Pathologic stage, Pathologic M stage, Pathologic N stage, Histologic grade, Laterality, and OS event, suggesting that CD72 may play an essential role in the biological function of tumor cells." (PMID 37980541, 2023). "Nanobody‐based CAR‐T cells can function as an antitumor agent in tumor microenvironment and tumor xenograft models, such as CD19 CAR‐T, CD70 CAR‐T, CD72 CAR‐T, CD105 CAR‐T, which are engineered by CRISPR/Cas9 and in silico techniques." (PMID 40536197, 2025). "ANGPTL4, LTB4R, CD72, and NUDT6 were downregulated, as their expression levels were higher in the healthy group and lower in the tumor group." (PMID 36911403, 2023). "For six of the genes (CCT5, CD72, COL10A1, FAM177A1, SLC25A12 and TDP1), we were unable to identify a correlation (i.e. concordance) between the copy number alteration and gene expression in six of the tumour samples tested." (PMID 25884485, 2015).
infection (8 papers, 2018 to 2023). The state of being infected such as from the introduction of a foreign agent such as serum, vaccine, antigenic substance or organism. "Unswitched memory B cells had a significant reduction in CD72 expression during severe SARS-CoV-2 infection when compared to mild infection, vaccination, or healthy controls." (PMID 37638016, 2023). "Accordingly, CD72 was expressed at a significantly lower level on DN2 cells from severe SARS-CoV-2 infection compared to DN2 cells after immunization or those with mild infection." (PMID 36131937, 2022). "However, when anti-CD72 antibody is added before sCD100, infection levels returned to basal levels." (PMID 29922261, 2018). "Similar to WT STm infection, genes involved in the regulation of immune responses (ATF3, BATF3, ETS2, IRF9, NFκB2, MAFA, TNFAIP3), effector functions, (CCL4, CD200L, CD40, CD72, CD80, IL18) and TLR signaling, (EAF2, TLR15, TRAF3IP2, TOLLIP) were upregulated after ΔprgH STm infection in both models." (PMID 37854334, 2023). "Likewise, B cell differentiation genes (BCL10, CD72, FOS, PTPRC, SH3BP5, PTPN6, etc.)were also downregulated throughout the infection, correlating with the drop of B cell numbers at D8." (PMID 37146079, 2023). "Together, these data indicate that while CD72 expression is depressed with severe SARS-CoV-2 infection, the expression of the CD22 and FCRL5 inhibitory receptors on DN2 cells does not change with severe infection." (PMID 36131937, 2022).
immune diseases (1 paper, 2022). "CD72 is a co-receptor of BCR and an important regulator in the pathogenesis of several immune diseases; it plays a role in various B cell biological processes, including proliferation, apoptosis, and differentiation." (PMID 35957889, 2022).
CD72 also shares sentences with these, for which no sentence is quoted: lupus erythematosus (2 papers); Miscarriage (2); Primary Immunodeficiency (2); atherosclerosis (1); B-cell acute lymphoblastic leukemia (1); breast carcinoma (1); cholesteatoma (1); colon adenocarcinoma (1); colon cancer (1); diffuse midline glioma (1); hematological disease (1); immune deficiencies (1); Kawasaki disease (1); lupus-like syndrome (1); metastatic tumors (1); nephritis (1); rheumatoid arthritis (1); scleroderma (1).